ILF2 (interleukin enhancer binding factor 2)
Description:
Chromatin-interacting protein that forms a stable heterodimer with interleukin enhancer-binding factor 3/ILF3 and plays a role in several biological processes including transcription, innate immunity or cell growth. Essential for the efficient reshuttling of ILF3 (isoform 1 and isoform 2) into the nucleus. Together with ILF3, forms an RNA-binding complex that is required for mitotic progression and cytokinesis by regulating the expression of a cluster of mitotic genes. Mechanistically, competes with STAU1/STAU2-mediated mRNA decay. Also plays a role in the inhibition of various viruses including Japanese encephalitis virus or enterovirus 71. (Microbial infection) Plays a positive role in HIV-1 virus production by binding to and thereby stabilizing HIV-1 RNA, together with ILF3.
Synonyms: NF45; PRO3063
Tractability: Antibody: its Gene Ontology location is reachable by antibodies, with high confidence. PROTAC: UniProt records ubiquitination sites on it; ubiquitination databases record sites on it; its protein half-life has been measured.
Gene: Protein-coding gene on chromosome 1 (153,661,788 to 153,671,028, reverse strand). Ensembl gene ENSG00000143621.
Subcellular location: Nucleus, nucleolus; Cytoplasm; Nucleus
Subcellular location (Human Protein Atlas): Nucleoplasm; Cytosol
Pathways (Reactome):
Immune System: Neutrophil degranulation; PKR-mediated signaling
Gene Ontology:
Molecular function: DNA binding; double-stranded RNA binding; protein binding; RNA binding
Biological process: positive regulation of DNA-templated transcription
Cellular component: cytoplasm; cytosol; extracellular region; membrane; nucleolus; nucleoplasm; nucleus; ribonucleoprotein complex; ficolin-1-rich granule lumen; specific granule lumen; tertiary granule lumen
Genetic constraint (gnomAD): Loss-of-function variants: 7 observed, 40.59 expected, observed/expected ratio (o/e) 0.17, 90% interval 0.097 to 0.32. The upper end of that interval is the gene's LOEUF score, 0.32, which puts it in group 1 of 6, group 1 being the genes least tolerant of losing a copy. Missense variants: 234 observed, 399.25 expected, observed/expected ratio (o/e) 0.59, 90% interval 0.53 to 0.65. Synonymous variants: 115 observed, 137.93 expected, observed/expected ratio (o/e) 0.83, 90% interval 0.72 to 0.97.
Homologues: Orthologues: chimpanzee ILF2 (100% identical), dog ILF2 (100% identical), mouse Ilf2 (100% identical), guinea pig ILF2 (99% identical), rabbit ILF2 (99% identical), macaque ILF2 (99% identical), pig ILF2 (99% identical), chimpanzee ILF2 (92% identical), zebrafish ilf2 (89% identical), rat Ilf2 (82% identical), tropical clawed frog ilf2 (76% identical), Drosophila melanogaster CG5641 (57% identical), and 1 more. Paralogues in human: ZFR2 (24% identical), ZFR (24% identical), ILF3 (23% identical), STRBP (21% identical), ADARB1 (17% identical), ADAR (16% identical), ADAD2 (15% identical), ADARB2 (15% identical), ADAD1 (15% identical), ADAT1 (11% identical), STAU2 (11% identical), TARBP2 (9% identical), and 2 more.
Diseases named in the same sentence as ILF2 in open-access papers:
ILF2 is named in the same sentence as 65 diseases in open-access papers, as found by Europe PMC text mining. Sharing a sentence is not in itself a finding about the gene and the disease. The quoted sentences say what the papers report.
breast carcinoma (8 papers, 2021 to 2025). "In breast cancer, high ILF2 expression is associated with an increased risk of recurrence, distant metastasis, and death." (PMID 39735599, 2024). "ILF2 acts as a tumor promoter, with overexpression associated with poor prognosis in CC, pancreatic ductal adenocarcinoma, non-small cell lung cancer and breast cancer." (PMID 34026616, 2021). "Thus, reduced expression of H19 or ILF2 might serve as a biomarker for determining breast cancer patients with BRCA1 deficiency or low BRCA1 for consideration for use of PARP inhibitors for adjuvant therapy." (PMID 37298108, 2023). "To monitor the in vivo behaviour of tumour cells, we performed bioluminescence imaging (BLI) of luciferase‐tagged ILF2‐KD breast cancer cells." (PMID 38943472, 2024). "A unique short hairpin RNA (shRNA) was utilised to effectively and stably suppress ILF2 expression (ILF2‐KD) in breast cancer cells." (PMID 38943472, 2024). "Additionally, K–M analyses indicated that ILF2 was an unfavourable prognostic factor in breast cancer." (PMID 38943472, 2024). "The suppression of ILF2 expression leads to improved prognosis in breast cancer." (PMID 38622522, 2024). "Notably, after the cells were injected into mice via the internal carotid artery, the ILF2‐KD group exhibited significant inhibition of breast cancer cell growth." (PMID 38943472, 2024). "Furthermore, evidence has been presented that H19 depletion increases sensitivity to PARP inhibitors via ILF2 in ER+ breast cancer cells with wild-type BRCA1 and in BRCA1 mutant triple-negative breast cancer cells." (PMID 37298108, 2023). "Therefore, it is apparent that H19 regulates breast cancer cell sensitivity to PARP inhibition via binding to ILF2." (PMID 37298108, 2023). "Therefore, targeting the H19/ILF2/BRCA1 axis might modulate therapeutic approaches in breast cancer." (PMID 37298108, 2023). "In conclusion, our study demonstrated that LINC00571 was highly expressed in breast cancer, and promoted cancer cell proliferation through the HNRNPK/ILF2-TCA cycle axis." (PMID 38238853, 2024). "In conclusion, this study demonstrated that lncRNA H19 directly binds to ILF2 and thereby co-regulates DNA damage response and sensitivity to PARP inhibitors in breast cancer." (PMID 37298108, 2023). "We map the presence of splicing-related genes in breast cancer, describing three novel genes, LSM1, CLNS1A, and ILF2, that have an oncogenic role and can be modulated with BET inhibitors." (PMID 34439272, 2021). "Studies have shown high ILF2 expression in esophageal squamous cell carcinoma (ESCC), hepatocellular carcinoma (HCC), non-small-cell lung cancer (NSCLC), pancreatic ductal adenocarcinoma (PDAC), gastric cancer, breast cancer, and gliomas." (PMID 39735599, 2024). "Moreover, when the presence of CNAs in our selected genes was analyzed in different tumor types (GDC Data Portal; 67 primary sites), breast cancer was one of most frequently amplified for LSM1, CLNS1A, and ILF2." (PMID 34439272, 2021). "Given the multi‐organ metastatic nature of breast cancer and the inherent heterogeneity of cancer cells, we established mouse models of metastasis by injecting MDA‐MB‐231 cells into BALB/c nude mice to determine whether ILF2 was upregulated in BCBrM in vivo." (PMID 38943472, 2024).
glioma (8 papers, 2009 to 2024). A benign or malignant brain and spinal cord tumor that arises from glial cells (astrocytes, oligodendrocytes, ependymal cells). "In gliomas, ILF2 expression correlates with higher World Health Organization grades, suggesting a role in glioma progression." (PMID 39735599, 2024). "Overexpression of ILF2 was frequently observed in non-small cell lung cancer, glioma, childhood endodermal sinus tumors, ESCC, and hepatocellular carcinoma." (PMID 36717549, 2023). "And high expression of ILF2, which was observed in glioma, cervical cancer, esophageal squamous cell cancer, and bladder cancer, was significantly related to the poor prognosis of these malignant tumors." (PMID 35333683, 2022). "Recent evidences indicate that ILF2 is highly expressed in non-small-cell lung cancer, glioma, lymphoma, leukemia, and cervical cancer, and high expression of ILF2 is associated with poor clinical outcome." (PMID 30881868, 2019). "A growing pool of evidence has indicated that overexpression of ILF2 is frequently observed in glioma, non-small cell lung cancer, esophageal squamous cell carcinoma, and childhood endodermal sinus tumors and is related to poor clinical outcomes." (PMID 27556459, 2016). "Furthermore, it was reported that ILF2 had similar functions in other malignant tumors such as gliomas and non-small-cell lung cancer." (PMID 28831206, 2017). "In addition to HCC, increased ILF2 expression has also been detected in glioma, non-small cell lung cancer, and esophageal cancer." (PMID 27556459, 2016).
viral infection (8 papers, 2014 to 2025). "For example, over half of these genes have been previously associated with viral infection or replication, or have been found to physically interact with viral proteins (e.g. CLDN3; CRHR2; ILF2; ILF3; LTF; miR-122; RCHY1; and, RUVBL2)." (PMID 25079789, 2014). "ILF2 regulates viral replication and plays a key role in inhibiting viral infection." (PMID 41375555, 2025). "And although ILF2 plays critical roles in the repression of viral infection, the mechanism by which virus antagonizes ILF2-mediated antiviral effects was unknown until this study." (PMID 31878072, 2019). "One of mechanisms underlying RDUR function is likely through formation of a complex with ILF2/ILF3 that might regulate the translation of IFN-β1 and some ISGs during the viral infection." (PMID 34054851, 2021).
cervical carcinoma (7 papers, 2016 to 2025). A carcinoma arising from either the exocervical squamous epithelium or the endocervical glandular epithelium. "Furthermore, ILF2 is implicated in the regulation of HPV gene expression in cervical cancer, particularly the E6 and E7 oncogenes, which are critical in cervical carcinogenesis." (PMID 39735599, 2024).
gastric cancer (7 papers, 2017 to 2024). A primary or metastatic malignant neoplasm involving the stomach. "In this study, we utilized cross-omics analysis and identified ILF2 as a promising serum diagnostic marker for gastric cancer, exhibiting good diagnostic value and applicability." (PMID 38622522, 2024). "ILF2 levels were significantly elevated in the serum of gastric cancer patients, demonstrating its diagnostic significance." (PMID 38622522, 2024). "Trans-omics analysis of proteomics and transcriptomics is an efficient approach for discovering serum biomarkers, and ILF2 is a potential diagnostic biomarker and therapeutic target of gastric cancer." (PMID 38622522, 2024). "In gastric cancer, high ILF2 expression is associated with deeper invasion, lymph node metastasis, advanced TNM stage, and poor differentiation, affecting both DFS and OS." (PMID 39735599, 2024). "The study concluded that ILF2 expression could be used to predict recurrence risk and overall prognosis in gastric cancer patients." (PMID 39735599, 2024). "Furthermore, the diagnostic significance of serum ILF2 concentration for gastric cancer should be validated through large-sample and multicenter studies." (PMID 38622522, 2024). "Overexpression of ILF2 significantly promotes the proliferation and colony formation of gastric cancer cells." (PMID 38622522, 2024). "Although we have successfully screened and validated ILF2 as a valuable biomarker for gastric cancer through rigorous multistep screening and validation, a larger sample size and multicenter validation of the results are still needed." (PMID 38622522, 2024). "In vitro experiments confirmed that ILF2 is highly expressed in gastric cancer cells and influences cell growth." (PMID 38622522, 2024). "Bioinformatics analysis revealed a significant correlation between ILF2 and immune status and therapeutic response in gastric cancer." (PMID 38622522, 2024). "We utilized the GDSC database to analyze the variations in response to standard chemotherapy drugs (5-fluorouracil, paclitaxel, docetaxel, and cisplatin) among gastric cancer patients with different levels of ILF2 expression." (PMID 38622522, 2024). "Recently, a great deal of studies have indicated that ILF2 was upregulated in numerous cancers, such as non-small cell lung cancer, gastric cancer and pancreatic carcinoma." (PMID 35333683, 2022). "The aim of this study is to investigate the expression levels and clinical significance of ILF2 in gastric cancer." (PMID 28831206, 2017). "The mRNA and protein expression of ILF2 in gastric cancer were examined for the first time in this research." (PMID 28831206, 2017). "However, there are still several related issues that require clarification, including the secretion mechanism of ILF2 from gastric cancer cells and the precise mechanism by which ILF regulates the biological behaviors of gastric cancer." (PMID 38622522, 2024). "Additionally, in-depth research is required to understand how ILF2 regulates the biological behaviors of gastric cancer and assess the influence of ILF2 expression on migration, invasion phenotypes, and immune modulation in gastric cancer." (PMID 38622522, 2024). "Moreover, the knockdown of ILF2 expression inhibited cell proliferation and colony formation, and overexpression of ILF2 promoted the proliferation and colony formation of gastric cancer cells." (PMID 38622522, 2024). "Furthermore, the overexpression of ILF2 in tumor tissues had substantial prognostic significance in gastric cancer." (PMID 38622522, 2024). "Recent studies have shown that ILF2 expression is significantly upregulated in esophageal cancer, lung cancer, gastric cancer, and other malignant tumors, which can promote tumor development and tumor cell proliferation, affect the cell cycle, and induce epithelial-mesenchymal transition." (PMID 39735599, 2024). "Thus, a larger number of tissue samples are needed to exhibit the clinical significance of ILF2 in gastric cancer." (PMID 28831206, 2017).
gastric cancer (continued). "However, the expression level of ILF2 in gastric cancer is not yet completely understood." (PMID 28831206, 2017). "Previous studies demonstrated the potential link between reduced ILF2 expression and decreased DNA damage repair (DDR) in multiple myeloma and gastric cancer." (PMID 34709752, 2021).
multiple myeloma (6 papers, 2019 to 2023). "In multiple myeloma, increased ILF2 is associated with therapeutic resistance mediated through DNA repair pathways, and it is interesting to note that increased expression of NUSAP1 is associated with DNA repair pathways in the PRAD data in our study and others." (PMID 37047232, 2023). "ILF2 had been previously identified by MS to be associated with RNA/DNA hybrids and has been shown to promote DNA repair through post-transcriptionally modulating DNA damage-induced splicing in multiple myeloma." (PMID 37047232, 2023). "In multiple myeloma, 1q21 amplification enhances ILF2 expression, which promotes resistance to melphalan." (PMID 34709752, 2021). "In addition to roles that are in common with ILF3, ILF2 also shows specific functions in tumorigenesis: In 1q21 amplified multiple myeloma, 1q21-driven ILF2 binds to YB1, interacts with the splicing factor U2AF65, and influences transcription of DNA damage response factors." (PMID 36012592, 2022). "Another study showed that ILF2/YB‐1/U2AF2 complex promotes DDR‐related mRNA processing that affects the expression of FANCD2 and EXO1 in multiple myeloma." (PMID 34709752, 2021).
hepatocellular carcinoma (5 papers, 2016 to 2025). A malignant tumor that arises from hepatocytes. "However, until now, little has been known about the detailed role ILF2 plays in hepatocellular carcinoma (HCC)." (PMID 27556459, 2016).
liver cancer (5 papers, 2016 to 2025). An epithelial or non-epithelial malignant neoplasm that arises from the liver. "Taken together, our findings uncover a new phenomenon that the relationship between CREB and ILF2 promotes liver cancer growth, and ILF2 only stimulates CREB in the protein level." (PMID 30881868, 2019). "The phenomenon of high expression of CREB and ILF2 proteins in liver cancer tissues compared to adjacent normal liver tissues was also observed." (PMID 30881868, 2019). "In the current work, we emphasized the importance of CREB and ILF2 in stimulating malignant phenotypes of liver cancer cells." (PMID 30881868, 2019). "Based on the expression patterns of ILF2 in the liver cancer cell lines, MHCC-LM3 and Huh7 were selected to perform the experiments." (PMID 27556459, 2016). "Taken together, these results demonstrate the ability of ILF2 to modulate the proliferative capacity of liver cancer cells in vivo." (PMID 27556459, 2016). "To explore its potential role in HCC proliferation, we utilized small interfering RNA (siRNA) transfection and lentivirus overexpression methods to remove the endogenous ILF2 and enhance the expression of exogenous ILF2 in liver cancer cells, respectively." (PMID 27556459, 2016). "Similar to that observation, our results showed upregulation of ILF2 in HCC and that ILF2 plays a significant role in liver cancer cell growth in vitro and in vivo." (PMID 27556459, 2016). "Next, we demonstrated the effects of ILF2 silencing and overexpression on the proliferation of liver cancer cells by Cell Counting Kit-8 (CCK-8) assay and colony formation assay." (PMID 27556459, 2016). "Higher levels of ILF2 were observed in liver cancer cell lines than in a normal liver cell line (LO2)." (PMID 27556459, 2016). "Data presented here indicate that ILF2 plays a significant role in liver cancer cell growth, cell proliferation, and survival." (PMID 27556459, 2016). "If CREB is inhibited in liver cancer, ILF2 would lose its ability as a liver cancer stimulator." (PMID 30881868, 2019). "Taken together, our study finds a novel interaction between CREB and ILF2 in liver cancer, and this interaction might play a role in the diagnosis and remedy of liver cancer." (PMID 30881868, 2019). "Interleukin enhancer binding factor 2 (ILF2) has become research hotspot in liver cancer recently." (PMID 30881868, 2019). "Liver cancer cells would grow rapidly when infected with ILF2 overexpression plasmids." (PMID 30881868, 2019). "Subcellular tissue proteomics also regards ILF2 as a molecular stimulus of liver cancer." (PMID 30881868, 2019). "Here we show that ILF2 might regulate Bcl-2 and cIAP1 expression in xenografted tumors and liver cancer cells, suggesting that the oncogenic function of ILF2 was at least in part by promoting the expression of Bcl-2 and cIAP1." (PMID 27556459, 2016). "Expression of ILF2 may regulate cell growth and apoptosis in liver cancer cells via regulation of B-cell lymphoma 2 (Bcl-2), Bcl-2 related ovarian killer (Bok), Bcl-2-associated X protein (BAX), and cellular inhibitor of apoptosis 1 (cIAP1)." (PMID 27556459, 2016). "Next, to determine whether the increase in cell proliferation was due to inhibition of apoptosis and how ILF2 expression correlates with apoptosis in liver cancer cells, we performed an apoptosis assay by flow cytometry." (PMID 27556459, 2016). "Moreover, we inoculated nude mice with liver cancer cells to investigate the effect of ILF2 on tumorigenesis in vivo." (PMID 27556459, 2016). "Together, these results suggest that ILF2 might be involved in liver cancer cell proliferation and apoptosis." (PMID 27556459, 2016). "Targeting this ILF2-CREB interaction might provide new strategies for liver cancer treatment." (PMID 30881868, 2019). "Therefore, ILF2 acts as a liver cancer stimulator mainly through its regulation on CREB." (PMID 30881868, 2019).